PGR (progesterone receptor)
Diseases named in the same sentence as PGR in open-access papers (continued):
Sharing a sentence is not in itself a finding about the gene and the disease.
breast cancer (continued). "However, we also found several candidate miRNAs which could be potentially associated with either an ER(−)/PgR(+) or an ER(+)/PgR(−) subtype of breast cancer, which may indicate their biological importance in these tumors." (PMID 32825530, 2020). "Therefore, polymorphisms in PGR that effect its level of expression may be associated with variations in the risk of breast cancer." (PMID 29370776, 2018). "However, FIZ1 expression in breast cancer is statistically associated with progesterone receptor status, estrogen receptor status, and sample subtype, and it undergoes extensive CpG-island methylation, and it is therefore an intriguing candidate for further study." (PMID 30483308, 2018). "Pregnancy is associated with a transient increase in risk of breast cancer for up to a decade post delivery, and subsequently confers a protective effect for women younger than 30 at first birth and for estrogen receptor (ER) and progesterone receptor (PR) positive tumors." (PMID 28720108, 2017). "Moreover, copy number loss of the PGR gene is a common feature in ERα + breast cancers, and may explain lower PgR levels in a subset of cases." (PMID 26970778, 2016). "Thus, the expression of estrogen and progesterone receptor in the breast cancer primaries is associated with better survival analyzed from the time point of first diagnosis (ER HR: 0.09 95 % CI [0.01–0.56], p = 0.0015 and PGR HR: 0.21 95 % CI [0.05–0.92], p = 0.0245)." (PMID 26862065, 2016). "We also note that the expression of PgR in breast cancer tumors can vary across the area of the tumor, and the role of intratumoral heterogeneity of PgR expression may complicate any associations observed between lipoproteins and breast cancer prognosis." (PMID 26970778, 2016). "Accordingly, we attempted to elucidate the effects of PINO on human mammary cells with different oestrogen and progesterone receptor expression, to determine whether this compound may contribute, at least in part, to the reduced incidence of breast cancer associated with VOO consumption." (PMID 27604292, 2016). "However, there is some evidence that the impact of lifestyle factors like PA on breast cancer risk may vary by tumor characteristics, such as estrogen receptor (ER) and progesterone receptor (PR) status." (PMID 24580799, 2014). "Hormone suppression in postmenopausal women with estrogen or progesterone receptor positive breast cancers has been associated with significant benefits such as decreased local and distant recurrences, a lower risk of contralateral breast cancer and improved breast cancer specific mortality." (PMID 23520572, 2013). "No prognostic significance could be seen for cytoplasmic 4EBP1 (data not shown), but the variable 4EBP1cytoplasm ≥ nucleus was an independent prognostic factor, predicting increased risk of distant recurrence and breast cancer death, especially among patients with PgR-expressing tumours." (PMID 24131622, 2013). "Interestingly, in a xenograft model of ER(+)/HER2 overexpressing breast cancer, the loss of the ER protein and deregulation of the progesterone receptor with increased mucins, especially MUC4, which has been associated with endocrine resistance in breast cancer, has been observed." (PMID 23344024, 2012). "These cell lines which are positive for estrogen receptor (ER), progesterone receptor (PR) and C-erbB-2, could provide us with new experimental materials to study the pathogenic mechanism and to screen for new therapeutic reagents against breast cancer." (PMID 19121212, 2009). "Moreover, an increased PRA/PRB ratio in breast cancer cells has been shown to induce changes in cell morphology and the loss of cell adhesion in response to progesterone receptor agonists, along with a membrane-to-cytoplasm redistribution of the ERM protein, ezrin." (PMID 18665217, 2008).
breast cancer (continued). "In addition, since we recently observed a strong association between loss of WWOX expression and estrogen and progesterone receptor (ER and PR) status in breast cancer, we also investigated any potential association between expression of sex steroid hormone receptors and WWOX in ovarian cancer." (PMID 15982416, 2005). "Progesterone exerts its effect on target cells by interacting with its receptor; thus, genetic variations, which might cause alterations in the biological function in the progesterone receptor (PGR), can potentially contribute to an individual's susceptibility to breast cancer." (PMID 15535845, 2004). "The proportion of patients with a complete response to therapy was statistically significantly lower after menopause, and in those with HER2-negative breast cancer, moderate tumor differentiation, and high estrogen and progesterone receptor expression." (PMID 42196449, 2026). "Breast cancer is commonly categorized based on the expression of three molecular markers: estrogen receptor (ER), progesterone receptor (PR), and human epidermal growth factor receptor 2 (Her2)." (PMID 41563517, 2026). "Positive ER and PgR in breast cancer and positive ER in liver metastases were beneficial for survival." (PMID 41511682, 2026). "Breast cancer is subtyped based on ER, progesterone receptor (PR) and Human epidermal growth factor receptor 2 (HER2) status." (PMID 41596432, 2026). "This is especially concerning in the Zambian context given the evidence that most breast cancer cases, histologically determined to be estrogen/progesterone receptor positive, appear to occur below the age of 50 years." (PMID 41542064, 2026). "Herein, the environmental risks of BPs are deciphered by linking their structural affinity for the progesterone receptor (PR), a master regulator of breast cancer, to oncogenic outcomes across experimental tiers." (PMID 41201099, 2026). "Hormone receptor–positive (HR+) breast cancer (BC) constitutes 70%–75% of breast tumors, characterized by the expression of the estrogen receptor α (ER+) and the progesterone receptor (PR+)." (PMID 41289011, 2026). "For instance, In breast cancer tissues and plasma or serum, the expression of miR-155 is elevated and shows a negative correlation with the levels of estrogen receptor (ER) and progesterone receptor (PR)." (PMID 39963112, 2025). "Breast cancer classification depends on immunohistochemical staining to identify the presence of three crucial receptors: estrogen receptor (ER), progesterone receptor (PR), and human epidermal growth factor‐2 (HER2)." (PMID 41144937, 2025). "Current protocols are still based on three biomarkers, namely, HER2, oestrogen receptor, and progesterone receptor, to develop personalised treatment plans for breast cancer patients." (PMID 40177129, 2025). "TNBC lacks receptors such as human epidermal growth factor receptor 2 (HER2), Estrogen receptor (ER), and Progesterone receptor (PR), which are expressed in breast cancers." (PMID 40284424, 2025). "Based on molecular and histological properties, breast cancer can broadly be divided into three groups: luminal-type (estrogen receptor/progesterone receptor-positive (ER+)), human epidermal growth factor receptor 2 (HER2) positive, and triple-negative." (PMID 40723905, 2025). "Estrogen receptor (ER) and progesterone receptor (PR) pathways drive the majority of breast cancers, while androgen receptor (AR) signaling underpins the growth and progression of prostate carcinomas." (PMID 41228293, 2025). "ERα‐36 has also been identified as a regulator of progesterone receptor (PR) activity in breast cancer, exerting control over both signaling and transcriptional processes associated with progesterone, resulting in increased cell proliferation and migration." (PMID 39285617, 2025).
breast cancer (continued). "We aimed to utilize an LLM to identify a hypothetical “Luminal B poor-prognosis” breast cancer subgroup (LPP) based on progesterone receptor (PR), the Ki-67 proliferation index, and grade characteristics, while concurrently validating the LLM’s accuracy." (PMID 41375036, 2025). "The immunohistochemical analysis of HER2 with estrogen receptor (ER) and progesterone receptor (PR) is recommended for routine clinical practice in the management of breast cancer." (PMID 40391262, 2025). "ER+ (estrogen receptor) and PR+ (progesterone receptor) breast cancers belong to the subtype of hormone-dependent cancers." (PMID 39925739, 2025). "HER2-positive (+) breast cancer is a heterogeneous disease, accounting for 10–20% of all breast tumors, with approximately half cases expressing also estrogen receptor (ER) and progesterone receptor (PgR) at immunohistochemistry (IHC)." (PMID 40199689, 2025). "Following the 2010 revision of international guidelines redefining the cut-offs for estrogen and progesterone receptor positivity in breast cancer, the Swedish Breast Cancer Group (SweBCG) retained the ≥ 10% threshold." (PMID 41316480, 2025). "Studies have shown that patients with MBC are usually diagnosed at older age and at a more advanced stage and more likely to have estrogen receptor and/or progesterone receptor positive disease compared with female breast cancer (FBC) patients." (PMID 40710438, 2025). "Strong predictors of a therapeutic response in breast cancer are the estrogen receptor and progesterone receptor status and HER2 amplification, leading to the selection of anti-HER2 versus endocrine therapies." (PMID 39857048, 2025). "Immunostaining showed that her breast cancer had estrogen receptor (ER) and progesterone receptor (PgR) positivities (both Allred score 8), human epidermal growth factor receptor type 2 (HER2) negativity, and a low Ki-67 labelling index of 5%." (PMID 40395253, 2025). "Galloflavin, a derivative of gallic acid, is a significant antiglycolytic drug that inhibits both LDHA and LDHB in TNBC and estrogen receptor-positive/progesterone receptor-positive (ER +/PR +) breast cancer." (PMID 40295451, 2025). "Regarding breast cancer, reduced efficacy has been observed in ER+ patients, while higher efficacy has been noted in PgR− and HER2− patients." (PMID 41153631, 2025). "The treatment approach and prognosis for different types of breast cancer are determined by molecular subtypes on the basis of the expression of oestrogen receptor (ER), progesterone receptor (PR), and HER2 proteins." (PMID 39944834, 2025). "In the clinical setting, breast cancer is divided into four subtypes utilizing the expression levels of estrogen receptor (ER), progesterone receptor (PgR), and human epidermal growth factor receptor 2 (HER2)." (PMID 40643471, 2025). "Background/Objectives: The most common type of breast cancer (BRC) in women is estrogen/progesterone receptor positive." (PMID 39940314, 2025). "The most common type of breast cancer is estrogen and/or progesterone receptor-positive (i.e., hormone receptor-positive), which comprises approximately seventy percent of patients, with the majority occurring in postmenopausal women." (PMID 41044437, 2025). "Patients with luminal A-type breast cancer, characterized by hormone receptor positivity (HR+), particularly estrogen receptor-positive (ER+) and progesterone receptor-positive (PR+), often display low Ki67 expression." (PMID 40977686, 2025). "Approximately 70–80% of breast cancers are estrogen receptor-positive (ER+), with 65% of these cases also being progesterone receptor-positive (ER+PR+)." (PMID 40244377, 2025). "Triple-negative breast cancer (TNBC) (hereafter referred to as AR + TNBC) is an aggressive breast cancer subtype that lacks the expression of estrogen receptor (ER), progesterone receptor (PR), and human epidermal growth factor receptor 2 (HER2)." (PMID 40448099, 2025).
breast cancer (continued). "Breast cancer can be classified by the expression of estrogen receptor (ER) and progesterone receptor (PR) and amplification of human epidermal growth factor receptor 2 (HER2)." (PMID 40165290, 2025). "The Luminal subtypes, defined by estrogen receptor (ER) and/or progesterone receptor (PR) expression, are the most common form of breast cancer." (PMID 40519297, 2025). "Both progesterone receptor and estrogen receptor overexpression are assessed via immunohistochemistry (IHC) in order to inform the decision to use endocrine therapy for breast cancer." (PMID 39941808, 2025). "In breast cancer treatment, evaluating biomarkers—estrogen receptor (ER), progesterone receptor (PR), and human epidermal growth factor receptor 2 (HER2)—is strongly recommended in clinical guidelines, as they serve as key predictors of treatment outcomes." (PMID 41350189, 2025). "Therapy and survival of breast cancer patients are influenced by the tumorcharacteristics and the estrogen receptor, progesterone receptor, and HER2 statuses." (PMID 40862438, 2025). "Breast cancer is a heterogeneous disease that has classically been grouped based on the expression of estrogen receptor (ER) and progesterone receptor (PR) as well as the overexpression of human epidermal growth factor receptor 2 (HER2) in tumors." (PMID 40361362, 2025). "As a subtype of invasive breast cancer (IBC), luminal breast cancer is characterized by the expression of hormone receptors, particularly estrogen receptor (ER) and progesterone receptor (PR), and is typically HER2-negative." (PMID 40248531, 2025). "Luminal A breast cancer is defined as estrogen receptor (ER)- and/or progesterone receptor (PR)-positive, HER2-negative, and having low Ki-67 expression, indicating a lower proliferative rate." (PMID 40870508, 2025). "Gallen consensus, it was defined that the best cutoff for PgR positivity with characteristics of HR-positive breast cancer was at least 20%." (PMID 40002286, 2025). "TNBC is a type of breast cancer that shows low levels of estrogen receptor (ER), progesterone receptor (PR) and human epidermal growth factor receptor 2 (HER2) overexpression and/or gene amplification." (PMID 40508166, 2025). "Editing events were examined in the MCF7 breast cancer model, representing the most common type of breast cancer (luminal A subtype), expressing estrogen receptor (ER) and/or progesterone receptor (PR)." (PMID 40381037, 2025). "Molecular docking analysis revealed that Bayogenin binds to the progesterone receptor with a binding energy of -6.9 kcal/mol, suggesting its role in modulating breast cancer pathways." (PMID 40739477, 2025). "Most of the breast cancers were estrogen receptor positive and/or progesterone receptor positive, and few were ERBB2 positive (eTable 2 in Supplement 1)." (PMID 39745704, 2025). "Treatment strategies for breast cancer are tailored according to the expression of estrogen receptor (ER), progesterone receptor (PR), human epidermal growth factor 2 (HER2), and Ki-67 (the proliferation marker)." (PMID 40282854, 2025). "Hormone receptors, specifically the estrogen receptor (ER) and progesterone receptor (PR), as well as human epidermal growth factor receptor-2 (Her2), are tumor-specific markers extensively used to guide breast cancer therapy." (PMID 41155845, 2025). "Endocrine therapy that targets ER is the mainstay treatment in hormone receptor–positive (HR+) breast cancers, which express ER and/or the progesterone receptor (PR)." (PMID 40327396, 2025). "The main types of breast cancer include estrogen receptor-positive (ER+), progesterone receptor-positive (PR+), and human epidermal growth factor receptor-positive (HER2+)." (PMID 40075655, 2025).
breast cancer (continued). "Genetic correlation analysis revealed significant positive correlations between USP30 expression and ESR1 (estrogen receptor alpha) and PGR (progesterone receptor) levels in breast cancer samples." (PMID 41306556, 2025). "The molecules identified in the study stand out for presenting great interaction and being potential inhibitors of the human progesterone receptor as an alternative for the treatment of breast cancer in experimental trials (in vitro and in vivo)." (PMID 40005951, 2025). "Subtypes of breast cancer are based on the tumor cell expression of molecular markers, including estrogen receptor (ER), progesterone receptor (PR), and human epidermal growth factor receptor 2 (HER 2)." (PMID 40362529, 2025). "Breast cancer is classified into subtypes based on immunohistochemical biomarkers, including estrogen receptor (ER), progesterone receptor (PR) and human epidermal growth factor receptor 2 (HER2)." (PMID 39917621, 2025). "The ER-positive breast cancer was present in 113 cases (46.3%), while the PgR-positive breast cancer was present in 63 cases (25.8%)." (PMID 41316049, 2025). "Based on the expression pattern breast cancer is categorized into four subtypes i.e., progesterone receptor (PR), human epidermal growth factor receptor 2 (HER2), estrogen receptor (ER)." (PMID 39912983, 2025). "Breast cancer is classified into multiple subtypes, including hormone receptor‐positive (oestrogen/progesterone receptor, ER/PR), HER2‐positive (human epidermal growth factor receptor 2), and triple‐negative breast cancer (TNBC)." (PMID 40635123, 2025). "Breast cancer represents a significant health burden in Iraq, yet existing data on estrogen receptor (ER), progesterone receptor (PR), and human epidermal growth factor receptor 2 (HER2) status are limited." (PMID 40391262, 2025). "There are different molecular subtypes of breast cancer, defined by hormone receptor expression status (Estrogen receptor; ER, and Progesterone receptor; PR) and Human epidermal growth factor receptor 2 (HER2) status, affecting prognosis." (PMID 40652059, 2025). "Systemic therapy for breast cancer is commonly guided by classical immunohistochemistry markers such as the estrogen receptor, progesterone receptor, and HER2, which are conventionally used for breast cancer prognosis and classification." (PMID 40004017, 2025). "Among breast cancer cases, 74.3% were estrogen and progesterone receptor-positive and HER2-negative." (PMID 41294703, 2025). "The aggressiveness of breast cancer can be predicted by its subtype, which is based on the expression of the estrogen receptor (ER), progesterone receptor (PR), and the human EGF receptor 2 (HER2)." (PMID 41278204, 2025). "In clinical practice, breast cancer is classified into different subtypes based on the expression of hormone receptors (HRs), including estrogen receptor (ER) and progesterone receptor (PR), and human epidermal growth factor receptor 2 (HER2)." (PMID 40371348, 2025). "A total of 21 834 postmenopausal women with a stage 1-3 estrogen or progesterone receptor–positive breast cancer treated with primary surgery resulting in clear margins were identified between August 1, 2009 and December 31, 2015." (PMID 40838592, 2025). "In this prospective case–control study, postmenopausal women (n = 46) with newly diagnosed stage I-III estrogen and/or progesterone receptor-positive breast cancer were compared with healthy postmenopausal female controls (n = 22)." (PMID 41044437, 2025). "Breast cancer classification relies on the evaluation of hormone receptor status, including estrogen receptor (ER), progesterone receptor (PR), and human epidermal growth factor receptor 2 (HER2) expression." (PMID 41463075, 2025). "Breast cancer molecular classification is primarily determined by the expression of specific hormone receptors, including the estrogen receptor (ER), progesterone receptor (PR), and the human epidermal growth factor receptor 2 (HER2)." (PMID 40282199, 2025).